KRAS (KRas proto-oncogene, GTPase)
Diseases named in the same sentence as KRAS in open-access papers (continued):
Sharing a sentence is not in itself a finding about the gene and the disease.
cancer (continued). "The KRAS signaling pathway is tightly regulated in normal cells but is often hyperactivated in cancer cells due to KRAS gene mutations." (PMID 38481800, 2024). "Recently, lipid-bilayer nanodisc platforms and paramagnetic relaxation enhancement (PRE) analyses have revealed several distinct structures of the membrane-anchored homodimers of KRAS, an isoform that is most frequently mutated in human cancers." (PMID 38473778, 2024). "Recent work from several labs has highlighted the heterogeneous properties of KRAS alterations in human cancer, having successfully modelled a spectrum of KRAS mutations in relevant model systems." (PMID 38168062, 2024). "The occurrence of mutations in alternative codons varies, yet mutations outside of codon 12 constitute a notable portion of KRAS activating alleles in certain cancers." (PMID 39164274, 2024). "Take, for example, the frequent occurrence of KRAS mutations (KRAS is a proto-oncogene that encodes a GTPase) in cancer, a factor in >20% of human cancers." (PMID 39331730, 2024). "Mutations in the KRAS gene lock K-Ras into the ‘on’ state, resulting in uncontrolled cell growth that leads to cancer." (PMID 39720730, 2024). "The KRAS mutation stands out as one of the most influential oncogenic mutations, which directly regulates the hallmark features of cancer and interacts with other cancer-causing driver mutations." (PMID 39056802, 2024). "KRAS is the most highly mutated RAS isoform across cancers, accounting for ~85% of all RAS mutations with especially high frequencies in pancreatic and colorectal cancers." (PMID 39576860, 2024). "For example, KRAS is frequently mutated in several cancers and the G12C mutation locks KRAS into an active oncogenic state." (PMID 39544254, 2024). "From the development of selective inhibitors targeting specific KRAS mutations like G12C and G12D to pan-KRAS inhibitors and indirect KRAS modulators, the therapeutic arsenal against KRAS-driven cancers is rapidly expanding." (PMID 39456549, 2024). "In particular, HRAS and KRAS proto-oncogenes are good archetypes representing one of the most frequent oncoproteins associated with human cancer, with ∼20% of cancers driven by one or multiple point mutations in these genes." (PMID 39722416, 2024). "It is of note that the pattern of KRAS mutations differ among the different cancer types and KRAS mutations are usually represented by single-base missense." (PMID 39000238, 2024). "The result of KRAS mutation-positive A549 cells treated with BI-4020 suggested that driver mutation-positive cancers other than EGFR would be insensitive to BI-4020." (PMID 38396251, 2024). "An alternative approach to target cancer-specific neoantigens, such as KRAS mutations, involves leveraging T-cell receptors (TCRs) for T-cell-mediated cancer immunotherapy." (PMID 38684865, 2024). "The IMMUNOTARGET registry provides useful real-world guidance regarding ICI therapy in oncogene-addicted cancers, and it is important to emphasize that the benefits seen in this study were driven by KRAS mutations to a large extent." (PMID 38339280, 2024).
cancer (continued). "For example, researchers have developed CRISPR-based therapies that target specific mutations in genes such as KRAS, which is commonly mutated in many types of cancer." (PMID 38195537, 2024). "While KRAS mutations continue to drive high cancer diagnosis and death, researchers have developed unique strategies to target KRAS variations." (PMID 38841166, 2024). "The most commonly mutated gene families in cancer include the RAS gene family (KRAS, NRAS, and HRAS)." (PMID 38304870, 2024). "KRAS, the most frequently mutated oncogene in human cancer, produces two isoforms, KRAS4a and KRAS4b, through alternative splicing." (PMID 38354232, 2024). "Oncogenic mutations in RAS genes, particularly KRAS, are among the most common alterations in human cancers and have historically been considered “undruggable” due to the lack of suitable pockets for small-molecule binding." (PMID 39370455, 2024). "KRAS mutations are common in many cancers and are associated with significant changes in cellular metabolism, such as increased glucose uptake, enhanced glycolysis, and altered glutamine metabolism." (PMID 39001451, 2024). "Over the past decade, extensive research into compounds targeting cancer-related genes and signaling pathways, particularly those associated with KRAS mutations, has unveiled a close association between ferroptosis and various cancers." (PMID 38844964, 2024). "This patient cohort was treated at two large cancer centers, where 62 patients with G12C and 75 with other KRAS mutations were identified." (PMID 38339280, 2024). "The oncogenic KRAS mutations are the critical drivers of tumorigenesis in a variety of types of human cancers." (PMID 38473779, 2024). "KRAS is one of the most frequently mutated oncogenes in human cancers, playing a critical role in regulating cell growth, differentiation, and apoptosis." (PMID 38886570, 2024). "ASP3082 (Astellas Pharma) is a PROTAC that binds to KRAS G12D and E3 ubiquitin ligase, leading to selective KRAS G12D protein degradation and growth inhibitory activity in KRAS G12D-mutated cancer cells while sparing KRAS wild-type cancer cells." (PMID 39337530, 2024). "Among the various KRAS mutations in human cancers, G12C, G12D, G12V, and G12A are the most prevalent." (PMID 39704172, 2024). "In particular, the KRAS isoform is mutated in 84% of all RAS-mutant cancers, with a near 100% mutation frequency in PDAC." (PMID 38666907, 2024). "Our validation data with synthetic templates and genomic DNA from human cancer cell lines with KRAS variant mutations demonstrate the efficiency of PROMER PCR." (PMID 38938409, 2024). "Rat sarcoma (RAS) genes are the most commonly mutated oncogenes in human cancers, with Kirsten rat sarcoma (KRAS) being the most common subtype." (PMID 38734764, 2024). "Forty years since the initial discovery of KRAS mutation, numerous publications have highlighted the pivotal role of KRAS mutation in various cancers, including NSCLC." (PMID 39594840, 2024). "The KRAS-dependent cancer-promoting mechanism hinges mainly on mutations in the Gly12(G12)-coding region of the gene, which, in our research, predominated in BOT and lgOvCa alike." (PMID 39456660, 2024). "Adult with solid tumour, excluding melanomaLung cancers with KRAS G12C mutation,CRC and PDAC with KRAS mutations." (PMID 38807312, 2024).
cancer (continued). "Mutations in RAS (mainly KRAS) leading to its persistent activation are the most common mutations in cancer, appearing in nearly 30% of all cancer types." (PMID 38374954, 2024). "In contrast, KRAS mutated cancers are distributed throughout the colon tending to co-occur with APC mutations, with a higher tendency in the distal colon cancers." (PMID 38360902, 2024). "The MAPK/ERK pathway, frequently activated in cancers due to mutations in genes like KRAS, plays a vital role in cell proliferation and survival." (PMID 38473413, 2024). "KRAS is one of the most frequently mutated genes in cancer and one of the most sought after and valuable therapeutic targets." (PMID 38109937, 2024). "Activating mutations in RAS occur in ~20% of all cancers with the majority of these mutations occurring in KRAS." (PMID 39379700, 2024). "Specifically, we investigated the association of viral agents, including human papillomavirus (HPV) and Epstein–Barr virus (EBV), with KRAS G12D mutations in GI cancers to better understand their combined role in cancer development." (PMID 39673361, 2024). "In the MDA-MB-231 cancer cell line, already characterized by KRAS mutations, a heightened susceptibility and subsequent mortality is observed in response to both Lovastatin or Simvastatin treatments." (PMID 39217242, 2024). "For example, KRAS-mutated cancer cells secrete granulocyte macrophages and colony-stimulating factor, and this can induce myeloid-derived suppressor cell trafficking and inhibit the behavior of CD8 + T cells." (PMID 38684762, 2024). "In the case of cancer-associated KRAS research, the corresponding authors were distributed in 102 countries/regions." (PMID 38706597, 2024). "Recent evidence has demonstrated that modified and naked full length IgG antibodies are taken up and distributed in the cytoplasm in KRAS-mutated cancer cells through macropinocytosis/early endosomal escape and direct cell-penetrating mechanisms." (PMID 39179604, 2024). "Mutations in KRAS account for 86% of RAS-related cancers, including pancreatic, colorectal, and lung cancers." (PMID 38354232, 2024). "One-third of several human cancers are accompanied by mutations in KRAS genes and their dysregulated signaling pathways." (PMID 38730733, 2024). "Nevertheless, non-G12C mutants constitute most KRAS mutations in cancer, which prompts efforts to develop agents targeting broad KRAS mutants." (PMID 38872211, 2024). "KRAS is known as one of the most highly mutated proteins in human cancers, and KRAS mutants are well-established drivers of many tumorigenic processes." (PMID 38473778, 2024). "Mechanical evidence from animal models supports our findings, which suggest that a higher rate of KRAS mutation contributes to rapid cancer progression and metastasis." (PMID 38525415, 2024). "In the GSEA analysis, the hallmark gene sets related to KRAS signaling upregulation, epithelial-mesenchymal transition, hypoxia, and angiogenesis, which can play a role in cancer, appeared among the positively enriched gene sets (Supplementary 7)." (PMID 38979184, 2024). "We have demonstrated the applicability of the PROMER technology for the detection and quantification of KRAS mutations, which are clinically relevant for many cancers." (PMID 38938409, 2024). "Our identified hits have the potential to inhibit the KRAS G12D mutation and can help combat cancer." (PMID 38794122, 2024). "In the early stages of carcinogenesis, KRAS mutation promotes the survival, invasion, and migration of cancer cells." (PMID 38430394, 2024). "This study provides hope for the development of new drugs to treat the cancer caused by the KRAS G12D mutation." (PMID 38794122, 2024). "Such mutations are found in ~15% of all human cancers, highlighting the pivotal role of KRAS in oncogenesis." (PMID 38886570, 2024). "The RAS-regulated RAF–MEK1/2–ERK1/2 signalling pathway is activated in cancer due to mutations in RAS proteins (especially KRAS), BRAF, CRAF, MEK1 and MEK2." (PMID 38381045, 2024).
cancer (continued). "Clinically, the majority of KRAS-mutant cancers remain untreatable and those with treatable mutations are rarely cured." (PMID 38668053, 2024). "KRAS gene is the most frequently mutated oncogene in human cancers, with KRAS G12C occurring in 13% of all NSCLC cases in Western populations." (PMID 38920723, 2024). "Mutations in the KRAS gene are among the most common mutations observed in cancer cells, but they have only recently become an achievable goal for targeted therapies." (PMID 38397927, 2024). "Mutations in KRAS can disrupt the switch between active and inactive states thus promoting cancer development." (PMID 38515758, 2024). "Among several recognized cancer-related pathway drugs, low-risk scoring cases had significantly lower IC50s for KRAS (G12 C) inhibitor-12, JAK1_8709, Wnt-C59, and LY2109761, and higher sensitivity to AZ960." (PMID 38714855, 2024). "NRG1 expression plays a pivotal role in the progression of cancer, especially in the context of KRAS mutations." (PMID 38957319, 2024). "KRAS mutations are common in a variety of cancers, and they are considered to have some impact on the prognoses of cancer patients." (PMID 39010022, 2024). "Oncogenic KRAS mutations, especially at Codons G12, G13, and Q61, impair GTPase activity, leading to constitutive activation and aberrant signaling in cancer." (PMID 39056802, 2024). "This research provides nuanced insights into the multifaceted nature of KRAS-associated oncogenesis, highlighting the importance of considering various signaling pathways in understanding cancer development." (PMID 38465160, 2024). "An innovative approach to target KRAS-driven cancers is to accelerate the destruction of mutant KRAS alleles." (PMID 38576709, 2024). "KRAS is a prominent target in cancer therapy due to its significant role in various cancers, and the G12C mutation has been its most frequent and consequential mutation." (PMID 39043787, 2024). "In view of the paucity of data for Indian patients, we have sought to delineate baseline clinical characteristics, treatment courses, prognosis and outcomes of lung cancer patients with KRAS mutations at our hospital, a tertiary care cancer center in India." (PMID 38439805, 2024). "Recent developments in targeted therapies for KRAS mutations in the lung and other major cancers suggest potential cross-organ applicability." (PMID 39330006, 2024). "Yet, more recent literature using isogenic cellular model systems suggests that KRAS-mutated cancer cells are in fact more resistant to ferroptosis." (PMID 38908072, 2024). "Kirsten rat sarcoma viral oncogene homolog (KRAS) is an oncogene implicated in the pathophysiology of many cancers." (PMID 38481800, 2024). "We found that most mutations had higher risk of cancer returning (relapse-free survival) compared to patients with KRAS mutation and ROS1 had highest risk of cancer returning in our study." (PMID 39734710, 2024). "The efficacy of the first-in-class SUMO-activating enzyme E inhibitor TAK-981 (subasumstat) was assessed in multiple human and mouse KRAS-mutated cancer cell lines." (PMID 38992694, 2024). "KRAS G12D occurs in 30% of KRAS mutant cancers, making it more common than KRAS G12C mutations and yet there are still no approved pharmacological agents to directly target this." (PMID 39372214, 2024). "KRAS is one of the most frequently mutated genes in cancer, being observed in up to 30% of patients with NSCLC." (PMID 38183584, 2024).
cancer (continued). "TG01 is an experimental vaccine designed to provoke an immune response against cancer cells by targeting the seven most prevalent codon 12 and 13 oncogenic mutations in KRAS with synthetic RAS peptides." (PMID 39335494, 2024). "PDAC is considered the most RAS-addicted of all cancers with a near 100% KRAS mutation frequency, and KRAS mutations have been reported in more than 95% of the precancerous pancreatic intraepithelial neoplasia (PanIN)." (PMID 38287020, 2024). "The five-year Cancer-Specific Survival was significantly worse in cases with mutated BRAF or KRAS, with a p-value of 0.04, and this significance persisted in the multivariate analysis." (PMID 38786299, 2024). "The Sotorasib, an innovative covalent inhibitor targeting this mutation, represents a paradigm shift to KRAS-related cancer treatment." (PMID 39043787, 2024). "Owing to its prominence as the most frequently mutated gene in human cancers, KRAS has emerged as a central focus in drug discovery efforts, with current strategies targeting both splice variants." (PMID 38354232, 2024). "To elucidate the resistance mechanism, we conducted a comprehensive analysis using the FoundationOne CDx cancer gene panel test, revealing the presence of a KRAS Q61H mutation alongside the BRAF V600E mutation." (PMID 38962037, 2024). "According to the gene expression profiles, two cancer cell lines were chosen: BT-20 overexpressing EGFR with wild-type KRAS and ROSE 199 A2/5 bearing C12V mutation in KRAS with wild-type EGFR." (PMID 38374954, 2024). "Recent studies have revealed that cancer cells with KRAS mutations utilize amino acids such as glutamine and leucine to accelerate energy metabolism and redox balance through GSH synthesis and macromolecule biosynthesis." (PMID 38459595, 2024). "KRAS is so frequently mutated in cancer that it is considered the most common oncogenic gene driver." (PMID 38250839, 2023). "As the most frequently mutated oncogenes, KRAS-activated mutation is found in one out of every seven human cancers." (PMID 37110848, 2023). "Mutated KRAS, commonly referred to as an “undruggable target”, is a driver of various cancers and is associated with suppressed anti-cancer immunity." (PMID 36803614, 2023). "A KRAS mutation is an important driver leading to metabolic reprogramming in cancer cells, and it is closely related to glutamine and its metabolic changes." (PMID 36959802, 2023). "The upstream signal of RTK and SHP2 in cancers with KRAS mutations presents a novel target for RTK and SHP2 inhibitors." (PMID 38001644, 2023). "This, along with their widespread deregulation in many distinct cancers, has triggered enthusiasm for miRNAs as novel therapeutic targets for cancer management, in particular in patients with refractory cancers such as those harboring KRAS mutations." (PMID 37704611, 2023). "Among the RAS gene family, KRAS is a frequently mutated oncogene with specific frequencies of variation in different cancer types." (PMID 37021044, 2023). "Many patients with KRAS G12C mutated cancers will likely live longer, and better, because of it and its companion-competitor drug sotorasib." (PMID 36933199, 2023). "Among the KRAS mutant cancers, there is evidence to support that the G12C mutation confers a worse prognostic outcome." (PMID 38067288, 2023). "The cumulative incidence of CRC mortality was significantly higher for variant vs wild-type KRAS among patients with YO cancer (Gray test P = .02) and LO (Gray test P < .001)." (PMID 38032636, 2023). "Among the RAS protein family, KRAS is the most frequently mutated protein in human cancer, followed by NRAS and HRAS." (PMID 37895906, 2023).